RNU6-912P (RNA, U6 small nuclear 912, pseudogene)
Gene: Small nuclear RNA gene on chromosome 7 (65,814,672 to 65,814,775, forward strand). Ensembl gene ENSG00000200670.
Homologues: Orthologues: chimpanzee U6 (99% identical), macaque U6 (97% identical), pig U6 (86% identical), dog U6 (82% identical), pig U6 (81% identical). Paralogues in human: RNU6-1254P (97% identical), RNU6-1319P (95% identical), RNU6-241P (95% identical), RNU6-747P (95% identical), RNU6-1052P (94% identical), RNU6-1076P (94% identical), RNU6-1100P (94% identical), RNU6-1118P (94% identical), RNU6-1217P (94% identical), RNU6-355P (94% identical), RNU6-447P (94% identical), RNU6-705P (94% identical), and 1288 more.